CSHL1 (chorionic somatomammotropin hormone like 1)
Description:
May be a novel gestational hormone required to compensate for absence of other members of the GH/CS cluster during gestation.
Synonyms: CSHP1; CSL; hCS-L; CS-5; MGC149868; GHB4
Tractability: Antibody: UniProt places it where antibodies can reach, with high confidence; UniProt predicts a signal peptide or a membrane-spanning region; its Gene Ontology location is reachable by antibodies, with medium confidence.
Gene: Protein-coding gene on chromosome 17 (63,909,597 to 63,911,341, reverse strand). Ensembl gene ENSG00000204414.
Subcellular location: Secreted
Gene Ontology:
Molecular function: protein binding; growth factor activity; growth hormone receptor binding; hormone activity
Biological process: animal organ development; growth hormone receptor signaling pathway; positive regulation of receptor signaling pathway via JAK-STAT; response to nutrient levels
Cellular component: cytoplasm; endomembrane system; extracellular region; vesicle
Genetic constraint (gnomAD): Loss-of-function variants: 25 observed, 24.96 expected, observed/expected ratio (o/e) 1, 90% interval 0.73 to 1.4. The synonymous counts are far from expectation, so gnomAD's model fits this gene poorly and the ratio says little. Missense variants: 342 observed, 288.24 expected, observed/expected ratio (o/e) 1.19, 90% interval 1.09 to 1.3. Synonymous variants: 157 observed, 121.08 expected, observed/expected ratio (o/e) 1.3, 90% interval 1.14 to 1.48.
Homologues: Orthologues: chimpanzee GH1 (94% identical), macaque CSH2 (74% identical), macaque GHV (73% identical), pig GH1 (59% identical), rabbit GHB1 (59% identical), dog GH1 (59% identical), mouse Gh (56% identical), rat Gh1 (56% identical), guinea pig Gh1 (56% identical), tropical clawed frog gh1 (43% identical), tropical clawed frog gh2 (36% identical), zebrafish gh1 (32% identical). Paralogues in human: CSH2 (91% identical), CSH1 (90% identical), GH1 (79% identical), GH2 (75% identical), PRL (23% identical).
Diseases named in the same sentence as CSHL1 in open-access papers:
CSHL1 is named in the same sentence as 13 diseases in open-access papers, as found by Europe PMC text mining. Sharing a sentence is not in itself a finding about the gene and the disease. The quoted sentences say what the papers report.
gestational diabetes mellitus (1 paper, 2025). "Despite this, CSHL1 itself has until recently not been implicated as a key driver or biomarker in preeclampsia or other metabolic disorders of pregnancy such as gestational diabetes mellitus." (PMID 41444673, 2025).
CSHL1 also shares sentences with these, for which no sentence is quoted: infection (3 papers); neoplasia (2); cancer (1); co-infection (1); diarrheal disease (1); Lymphadenopathy (1); metabolic disorders (1); metastatic melanoma (1); metastatic tumors (1); myeloproliferative disease (1); preeclampsia (1); pregnancy (1).